PPARG (peroxisome proliferator activated receptor gamma)
Diseases named in the same sentence as PPARG in open-access papers (continued):
Sharing a sentence is not in itself a finding about the gene and the disease.
diabetes (continued). "Thiazolidines, a class of pharmaceutical agents primarily used for the treatment of type 2 diabetes mellitus, exert their effects through the agonistic activity of peroxisome proliferator-activated receptor gamma (PPARγ)." (PMID 41355896, 2025). "Approved and investigational therapies include PPARγ agonists (pioglitazone) for diabetes, FXR agonists (OCA) for liver disease, LXR modulators for atherosclerosis, and THR-β agonists (resmetirom) for MASH." (PMID 40926269, 2025). "Chrysin-6-C-fucopyranoside, isolated from a local cultivar of Cyclanthera pedata, has been identified as a novel and selective PPARγ agonist, indicating its potential in managing metabolic disorders like diabetes and hyperlipidemia." (PMID 40286240, 2025). "Because of its modulation of adipocyte differentiation and sensitization of adipocyte to insulin, PPARγ agonists, such as rosiglitazone and other thiazolidinediones, have been employed for the treatment of diabetes." (PMID 41019996, 2025). "According to these studies, the upregulation of PPARγ is a potential therapeutic pathway for managing diabetes." (PMID 40149950, 2025). "PPARγ agonists effectively control serum glucose levels in patients with diabetes, but some have been withdrawn because of adverse effects such as fluid retention, weight gain, and increased cardiovascular risk." (PMID 41357323, 2025). "Targeted by glitazone diabetes medications, PPARγ is frequently expressed in adipose tissue and influences both the arrival and departure of fatty acids to and from the liver, as well as the development of adipocytes." (PMID 39061866, 2024). "The PPI network indicated AKT1, IL-6 and PPARG as hub genes that are involved in the mechanism of diabetes." (PMID 39707185, 2024). "Clinically, they are routinely used as therapeutic agents such as fenofibrate, a PPARα agonist, for hyperlipidaemia, as well as pioglitazone, a PPARγ agonist for diabetes." (PMID 38993197, 2024). "We selected AKT1, IL-6, and PPARG as the core targets for gut microbiota metabolite regulation of diabetes based on their highest DC values." (PMID 39707185, 2024). "–69 Pioglitazone, an agonist of PPARγ used in the treatment of type 2 diabetes mellitus, has been shown to significantly protect RGCs and prevent axonal degeneration in the glaucomatous retina of mice." (PMID 38315494, 2024). "Starting from the early 2000s, the clinical use of TZDs as activators of PPARγ has significantly impacted the management of dyslipidemia and diabetes." (PMID 39199386, 2024). "In fact, PPARγ is an ‘old’ drug target and PPARγ agonist thiazolidinediones are used to treat type 2 diabetes mellitus for many years." (PMID 38365899, 2024). "The exact mechanism is still not fully clear but it is suggested that selective co-regulator recruitment to PPARγ is regulated in a phosphorylation-dependent manner and controls expression of diabetes-related genes." (PMID 38735390, 2024). "In contrast, recent studies have highlighted the cardioprotective role of PPARγ, leading to the use of several agonists to treat diabetes and its complications." (PMID 39867658, 2024). "PPARγ plays a critical role in regulating the metabolism of glucose and lipids, both of which are reduced in tissues during diabetes." (PMID 38924022, 2024). "It underscores the pivotal role of AMP-activated protein kinase (AMPK) in this interplay, drawing connections between diabetes mellitus, insulin, insulin-like growth factors, and peroxisome proliferator-activated receptor gamma (PPARγ) with PF." (PMID 38854692, 2024). "Rosiglitazone, a PPARγ agonist, has been evaluated in the context of diabetes-related and hyperlipidemia-related dry eye in mouse models." (PMID 38993197, 2024). "In this context, the identification of PPARγ partial agonists is a promising strategy for diabetes management." (PMID 38892571, 2024).
diabetes (continued). "The most common variant in the human PPARG gene is an alanine to proline substitution at position 12 in the PPARγ2 isoform (Pro12Ala) that has a variable physiological effect related to a decreased risk of type 2 diabetes mellitus (DM)." (PMID 39398333, 2024). "To investigate the pivotal role of PPARγ in diabetes-induced senescence of the vascular smooth muscle layer, we activated the PPARγ pathway in diabetic mice and vascular smooth muscle cells (VSMCs) through treatment with RSG (a known PPARγ agonist)." (PMID 38733164, 2024). "Pioglitazone, a drug used in the treatment of diabetes, has been shown to increase adiponectin by acting on PPARγ, which in turn activates AMP kinase, thereby decreasing blood glucose levels." (PMID 38545380, 2024). "Previous experimental studies had reported that TCDD increased hyperglycaemia via peroxisome proliferator activated receptor-gamma in a rat model of diabetes and that female mice exposed to TCDD during pregnancy had increased susceptibility to diabetes." (PMID 39072272, 2024). "Rosiglitazone, an insulin sensitizer formerly used in diabetes therapy, was used as a PPARG activator." (PMID 38098864, 2023). "Oral antidiabetic agents including the peroxisome proliferator-activated receptor gamma (PPARγ) agonists are available for the clinical management of diabetes mellitus (DM) but most are characterized by many adverse effects." (PMID 37200359, 2023). "The present study screened and evaluated phytoconstituents obtained from Trigonellafoenum-graecum as a potential agonist of PPARγ for the treatment of diabetes mellitus via an insilicocomputational approach." (PMID 37200359, 2023). "Rosiglitazone (RSG) is a peroxisome proliferator-activated receptor-gamma (PPARγ) agonist of the thiazolidinedione (TZD) class used to treat type 2 diabetes mellitus (T2DM) and potentially Alzheimer’s disease (AD)." (PMID 37508471, 2023). "Oroxin A also has the ability to activate PPARγ and inhibit α-glucosidase and is a promising candidate for diabetes intervention." (PMID 37525109, 2023). "Given the importance of PPARγ agonists in diabetes therapy, it is fundamental to take into account, however, the deep side effects caused by these drugs, such as oedema, headache, heart failure, hypoglycaemia, myalgias, and increased risk of fractures." (PMID 37049568, 2023). "Pioglitazone (PIO), a peroxisome proliferator-activated receptor-gamma (PPAR-γ) agonist, is utilized to treat diabetes mellitus type-2." (PMID 37934372, 2023). "In the increases in increases in the possibility of enhanced insulin sensitivity, as was also shown in a study investigating the effect of FK614 and pioglitazone, a thiazolidinedione PPARγ agonist in the Zucker fatty rat, an animal model for diabetes." (PMID 37893949, 2023). "Fibrates are PPARα modulators used for hyperlipidemia therapy and are represented by fenofibrate and pemafibrate, whereas thiazolidinediones, such as pioglitazone and rosiglitazone, are used for the treatment of diabetes through PPARγ agonism." (PMID 37893218, 2023). "For this reason, PPARγ agonist usually prescribed for the treatment of diabetes mellitus together with bisphosphate." (PMID 38031108, 2023). "PPARγ is highly relevant for diabetes control and plays a major role in Type 2 diabetes mellitus development." (PMID 36835226, 2023). "In detail, the master regulator of adipogenesis and prominent diabetes drug target, peroxisome proliferator-activated receptor γ (PPARG), will be debated as a potential therapeutic approach to enhance bone regeneration." (PMID 36895792, 2023). "PPARγ agonists have traditionally been used for the treatment of diabetes mellitus and other metabolic disorders." (PMID 37242695, 2023). "In particular, the thazolidinedione (TZD) drugs, such as rosiglitazone and pioglitazone, are strong PPARγ agonists, and became widely clinically used for diabetes treatment." (PMID 37886997, 2023).
diabetes (continued). "Gymnemic acid XII possesses a higher binding affinity to PPARγ, a promising drug target for diabetes." (PMID 36836796, 2023). "PPARγ agonists (thiazolidinediones) are used to treat Type 2 diabetes mellitus by improving insulin sensitivity." (PMID 36768666, 2023). "Prolonged use of thiazolidinediones, which are synthetic agents that activate PPARγ, has been correlated with an increased incidence of fracture in individuals with diabetes mellitus." (PMID 37513946, 2023). "Further, patients with diabetes treated with pioglitazone had a lower mortality rate compared to non-PPARγ agonists users." (PMID 37077349, 2023). "A retrospective study on veterans with both diabetes and COPD revealed that the risk of COPD exacerbations in patients receiving PPARγ agonists was significantly lower than that in patients receiving other diabetes medications." (PMID 37077349, 2023). "PPARγ itself is a highly druggable target, with agonists having been used for the past two decades in treating diabetes." (PMID 36510001, 2023). "Our group has recently identified that deacetylation of peroxisome proliferator-activated receptor γ (PPARγ), a target factor in diabetes treatment, possesses an endothelial-protective effect." (PMID 35260080, 2022). "Pioglitazone belongs to thiazolidinedione and is a highly selective PPARγ agonist found to reverse memory impairment and biochemical changes in a mouse model of type 2 diabetes mellitus and AD." (PMID 35684047, 2022). "A table of the six modification sites of PPARγ mentioned in this review and their function in diabetes are listed at the end of this section." (PMID 36551260, 2022). "Subsequently, highly specific PPARγ agonists were developed for the treatment of diabetes, and notably rosiglitazone emerged as a potent adipogenic stimulator." (PMID 36636339, 2022). "Pioglitazone is an agonist of the peroxisome proliferator-activated receptor γ (PPARγ) and has been widely used in the treatment of type 2 diabetes mellitus (T2DM) for several decades." (PMID 35176115, 2022). "PPARγ regulates glucose and lipid metabolism which was first used as a therapeutic target for diabetes." (PMID 36518993, 2022). "Due to its ability to reduce inflammatory parameters, the PPARγ agonist pioglitazone has also been proposed as an effective treatment for COVID-19 patients with diabetes, hypertension, and cardiovascular comorbidities." (PMID 36091002, 2022). "PPARγ (Peroxisome proliferator- activated receptor gamma) agonists (ciglitazone), while being widely used on patients of type 2 diabetes mellitus, also have approved anticancer effects." (PMID 36362294, 2022). "These critical roles of PPARγ, particularly in glucose homeostasis, make it an attractive drug target for the treatment of diabetes." (PMID 36339561, 2022). "LCN2 expression is elevated by agents that promote IR and is reduced by PPARγ agonists thiazolidinediones (TZDs), an important class of insulin sensitizers used in the treatment of diabetes." (PMID 36079831, 2022). "PPARγ agonists (such as thiazolidinediones) have been shown to delay DKD progression in patients with type 2 diabetes mellitus and in various animal models of diabetes." (PMID 35321238, 2022). "• Inhibition of adipocyte differentiation. • Increase of inflammatory molecules like COX2 and PEG2. • Induction of IL6 synthesis by adipocytes. • CDK5-dependent phosphorylation of PPARγ in adipocytes, favoring gene expression related to diabetes." (PMID 35422689, 2022). "Despite thiazolidinediones (TZDs), a class of PPARγ agonists, having been proven to be potent insulin sensitizers, their use is restricted in the treatment of diabetes for their adverse effects." (PMID 36551260, 2022). "In the present study, we aimed to investigate the effect of pioglitazone, a PPARγ agonist in the class of TZD, on the risk of IBD in patients with type 2 diabetes mellitus in Taiwan." (PMID 36558989, 2022).
diabetes (continued). "PPARγ is a target for insulin sensitizing drugs such as glitazones, which improve plasma glucose maintenance in patients with diabetes." (PMID 36558918, 2022). "Oral Pio, an agonist of PPARγ, is approved as an adjunct to diet and exercise to improve glycemic control in adults with type 2 diabetes mellitus (T2DM)." (PMID 35743273, 2022). "PPARγ agonism has a well-established beneficial role in the setting of diabetes, which has led to the generation of TZDs for the treatment of type II diabetes." (PMID 36359851, 2022). "PPARγ agonists are already being used in the treatment of conditions such as diabetes, where they act as insulin sensitizers." (PMID 36591308, 2022). "Thiazolidinedione, act as PPARG agonist, was limited used in patients with diabetes due to its effect of increasing sodium reabsorption, leading to fluid retention and edema." (PMID 36213291, 2022). "PPARG plays diverse roles in the pathogenesis of diabetes, regulating adipogenesis, lipid metabolism, insulin sensitivity, and inflammation." (PMID 35343389, 2022). "In particular, accumulating evidence suggests that, in addition to diabetes and metabolic syndrome, PPARγ agonists have significant therapeutic potential in brain disorders." (PMID 35956831, 2022). "Peroxisome proliferator-activated receptors (PPARs) are ligand-dependent transcription factors; drugs that activate the PPARγ subtype, increase insulin sensitization, and modulate glucose and lipid metabolism, commonly used to treat diabetes." (PMID 35684047, 2022). "Due to its role in glucose regulation, PPARγ agonists are suggested to ameliorate the problems of diabetes." (PMID 35807748, 2022). "Although the main role of PPARG is to focus on adipocyte differentiation and diabetes, many pieces of research have also demonstrated that PPARG has an important impact on the growth of various cancers." (PMID 34567087, 2021). "Since PPARγ agonists induce storage of fatty acids and glucose rather than consumption in the cell, the dual activation of PPARα and PPARγ is proposed to be more beneficial in managing metabolic diseases such as dyslipidemia of diabetes and fatty liver." (PMID 34593018, 2021). "Third, GLP-1 analogue like liraglutide, DPP-4 inhibitor like exenatide and sitagliptin, SGLT two inhibitor like empagliflozin, and PPARγ agonist like rosiglitazone are new anti-diabetes agents under development." (PMID 33995056, 2021). "Diabetes downregulated renal PPARγ expression in db/db mice and FGF1ΔHBS treatment significantly increased PPARγ transcription." (PMID 34149434, 2021). "The PPARG gene is expressed in liver hepatocytes, and its expression is correlated with fat accumulation in pathological conditions such as diabetes and NFLD." (PMID 35154608, 2021). "In comparison with rosiglitazone, which was a well-known drug for diabetes, the maximal isoflavone-induced PPARγ activity was between 23% and 32%." (PMID 33809928, 2021). "Recent studies have shown that some PPARG agonists retain insulin sensitization with few side effects and are widely used in the treatment of type 2 diabetes mellitus; ESR includes ESR1 and ESR2, and most of the effects of oestrogen are mediated by ESR1." (PMID 34164430, 2021). "Peroxisome proliferation-activated receptor γ (PPARγ), a transcriptional regulator, participates in the development of various diseases, including diabetes mellitus." (PMID 34336956, 2021). "Thiazolidinediones (TZDs), used to treat type 2 diabetes mellitus, act as full agonists of the peroxisome proliferator-activated receptor gamma." (PMID 35003235, 2021). "PPARγ is the molecular target of thiazolidinediones (TZDs), drugs used as insulin sensitizers to treat type 2 diabetes mellitus." (PMID 34071972, 2021). "Mushroom terpenoids act as inhibitors of α-glucosidase and as insulin sensitizers through activation of PPARγ in order to reduce hyperglycemia in animal models of diabetes." (PMID 33467194, 2021).
diabetes (continued). "A promising approach for treating type 2 diabetes mellitus (T2DM) is to target the Peroxisome Proliferator-Activated Receptor γ (PPARγ) transcription factor, which regulates the expression of proteins critical for T2DM." (PMID 34339734, 2021). "This study aimed to determine the relationship between PPARγ genotypes and phenotypes and to explore the pathogenesis of diabetes beyond this relationship." (PMID 34764936, 2021). "Pioglitazone in clinical use is thought to enhance peripheral insulin sensitivity as a diabetes therapeutic agent; however, these supportive data also demonstrate direct effects of PPARγ agonists in the functional preservation of β-cells." (PMID 34592314, 2021). "Among the PPAR family, PPARγ plays a central role in glucose homeostasis and adipocyte differentiation and has been related with diabetes mellitus." (PMID 34887761, 2021). "PPARγ activity is vital to the development and prevalence of type 2 diabetes mellitus (T2DM) due to its various roles in metabolism, particularly glucose homeostasis, which is dysregulated in T2DM." (PMID 34339734, 2021). "Our previous research also showed that PPARγ agonists reduced the serum inflammatory markers in patients with diabetes." (PMID 34484568, 2021). "Pioglitazone, which is one of the thiazoline derivatives, has been applied clinically as a PPARγ agonist with antidiabetic effects by enhancing insulin sensitivity for enhanced blood glucose control in diabetes." (PMID 34681744, 2021). "Instead of monotherapy with RXR agonists, the combination treatment of RXR and PPARγ agonists was shown to be more effective in increasing insulin sensitization and reducing hyperglycemia in murine models of obesity and non-insulin-dependent diabetes mellitus." (PMID 34680110, 2021). "Synthetic PPARγ agonists have been used as therapeutic agents for diabetes and insulin insensitivity." (PMID 32184808, 2020). "Kaempferol is a natural peroxisome proliferator-activated receptor-γ (PPARγ) agonist, and PPARγ agonists have become common drugs in the treatment of diabetes and its complications." (PMID 33178322, 2020). "A few studies have reported the efficiency of combined PPARα and PPARγ agonist therapy for diabetes and dyslipidemia." (PMID 32707656, 2020). "On a similar note, a gluten-free diet, which leads to increased expression of PPARα and PPARγ, was found to reduce diabetes incidence in NOD mice, even after exclusive exposure of the diet in utero." (PMID 32395123, 2020). "Peroxisome proliferator-activated receptor gamma (PPARγ- agonists, rosiglitazone and pioglitazone, are drugs in clinical use for diabetes." (PMID 32574268, 2020). "PPARγ agonists have been widely reported to improve glycemic status in diabetes patients, and PPARγ has favorable renal protective effects." (PMID 32774472, 2020). "But the use of PPAR agonists in diabetes treatment which mainly target PPARγ has been met with side effects." (PMID 32728045, 2020). "PPARγ activators have been used as type 2 diabetes mellitus treatment, acting as insulin sensitizers but with important secondary effects like increased lipogenesis or lipogenic intake in the liver, leading to steatosis." (PMID 32120804, 2020). "Beside diabetes treatments, PPARG activation decreases kidney fibrosis and inflammation and reduces retention of salt and water in renal tubules to prevent matrix expansion, thereby alleviating damage to kidney cells." (PMID 32604723, 2020). "Study showed that PPARγ is an important target for diabetes drugs, and its agonist can improve diabetes." (PMID 32265835, 2020). "We evaluated the transcriptional activity of peroxisome proliferator-activated receptor γ (PPARγ), a therapeutic target for diabetes, and analyzed PPARγ agonist activity of HODE isomers." (PMID 32266936, 2020).